CSF1R (colony stimulating factor 1 receptor)
Diseases named in the same sentence as CSF1R in open-access papers (continued):
Sharing a sentence is not in itself a finding about the gene and the disease.
colorectal cancer (continued). "This study mainly focused on the tumor infiltrating myeloid cells, and revealed the potential mechanism of immunotherapeutics targeting myeloid cells (anti-CSF1R and anti-CD40 agonism) in mouse models with colorectal cancers." (PMID 36172359, 2022). "Here, we extensively analyzed the expression of genes involved in immune response from 66 primary tumor samples of colorectal cancer (CRC) patients and compared the difference between patients with different CSF1R c.1085 genotypes." (PMID 34830445, 2021). "Patients with advanced colorectal cancer have considerably increased serum CSF1 levels, which may indicate a function for CSF1R signaling in the growth of CRC." (PMID 38725047, 2024).
dementia (28 papers, 2016 to 2026). Loss of intellectual abilities interfering with an individual's social and occupational functions. "Here we screened for variants in CSF1R gene in a large cohort of dementia patients consecutively referred for genetic analysis to an Italian tertiary center between 2005 and 2024 (n = 2163)." (PMID 41634195, 2026). "OAL-microglia in dementia models are characterized by high expression of the following genes: genes of CSF1R, IL-10, IL-12B, prostaglandin-E2 EP4 receptor (encoded by Ptger4 gene), c-Jun, and heat shock protein (HSP) family." (PMID 36969154, 2023). "One patient with a family history of cancer and dementia carried the CSF1R [MIM: 164770] c.2068G>A (p.Gly690Ser) variant in a Native American haplotype." (PMID 35260199, 2022). "Colony-stimulating factor-1 receptor -microglial encephalopathy, microglia-original dementia, is a rare autosomal dominant disease caused by mutations in the colony-stimulating factor-1 receptor (CSF1R) gene resulting in microglial dysfunction." (PMID 34955818, 2021). "Patient I carried a missense mutation in CSF1R TK flanking region (p.G957R) and displayed a different clinical picture, dominated by early-onset dementia (49 years) and language problems at the onset." (PMID 29544907, 2018). "Furthermore, considering the family history of dementia, genetic testing was subsequently carried out, which revealed a heterozygous c.2654 + 1G>A variant in the CSF1R gene." (PMID 40893935, 2025). "Likewise, Csf1 mRNA is increased in CSF1R-microglial-encephalopathy or glia-original dementia, a rare autosomal dominant disease caused by mutations in the gene coding for CSF1R resulting in microglial dysfunction." (PMID 36818562, 2023). "Furthermore, a compound heterozygous alteration of the TREM2 gene was identified in one patient and in two patients we found RDVs in other autosomal dominantly inherited genes also associated with dementia (CSF1R-ALSP, PRNP-CJD)." (PMID 35752680, 2022). "We estimate that CSF1R mutations account for 10% of idiopathic adult onset leukodystrophies and that genetic testing for CSF1R mutations is essential in adult patients presenting with undefined CNS vasculitis or a leukodystrophy with prominent neuropsychiatric signs or dementia." (PMID 25935893, 2016). "CSF1R mutation can result in amino acid changes in the tyrosine kinase domain (TKD) and microglial dysfunction, culminating in rapidly progressive dementia." (PMID 35721475, 2022). "All patients carrying variants in APP, CSF1R, ITM2B (p.Ile251Val), and NOTCH3 genes showed a family history for dementia." (PMID 33770234, 2021). "Neurologists should consider CSF1R-microglial encephalopathy when a patient exhibits early-onset rapid progressive dementia with symmetrical changes and persistent diffusion restriction in the deep white matter because the genetic spectrum of mutations is yet to be fully elucidated." (PMID 35721475, 2022). "CSF1R-microglial encephalopathy typically presents as rapidly progressive dementia." (PMID 34955818, 2021). "Moreover, thanks to NGS approach, we disclosed other variants in dementia-related genes, in particular FUS, ABCA7, CSF1R, DCTN1, SERPINI1 and SORL1." (PMID 33006056, 2021). "CSF1R gene mutations cause hereditary diffuse leukoencephalopathy with spheroids (HDLS), an autosomal‐dominantly inherited microgliopathy, leading to early onset dementia with high lethality." (PMID 30729751, 2019). "Therefore, it is strongly suggested that OAL contributes to the prevention of dementia by promoting m-CSF1 expression on peripheral leukocytes, activating CSF1R on microglia, and inducing transformation to neuroprotective microglia." (PMID 36969154, 2023). "Our findings suggest a targeted approach to restoring BBB integrity while also restoring CSF‐1R signalling in macrophages could drive a therapeutic response in ALSP patients and other AD‐like dementia." (PMID 33350588, 2021).
dementia (continued). "We show that dysregulated CSF‐1R‐dependent endothelial/microglial cell crosstalk induces re‐modelling of the BBB in mouse and human and suggests that regulating BBB integrity while promoting macrophage recruitment to the brain may be therapeutically viable in ALSP and other AD‐like dementia." (PMID 33350588, 2021).
ovarian carcinoma (28 papers, 2013 to 2025). A malignant neoplasm originating from the surface ovarian epithelium. "Increased expression of CSF-1 and CSF-1R has been associated with poor prognosis in clinical studies of epithelial ovarian cancer (EOC)." (PMID 39003350, 2024). "This restoration decreases the expression of critical functional molecular markers such as CSF1R and AR, which are potentially associated with an elevated risk for ovarian cancer." (PMID 39622842, 2024). "miR-449a and miR-449b-5p suppression of CSF1R and AR expression as a link to flutamide action and ovarian cancer risk reduction." (PMID 39622842, 2024). "The elevated expression of MCSF along with its receptor CSF1R in breast, uterine and ovarian cancer was associated with tumor progression." (PMID 24391839, 2013). "In addition, we analyzed the survival data of ovarian cancer patients in the high and low CSF-1R expression groups, and the results showed that the expression level of CSF-1R was significantly associated with the survival of ovarian cancer patients." (PMID 38303927, 2024). "High expression of CSF-1R in ovarian cancer was speculated to be closely associated with the invasion and metastasis of malignant tumors." (PMID 38303927, 2024). "Since miR-449a and miR-449b-5p suppress CSF1R and AR expression in ovarian cancer cells (SKOV3 and Hey) and CSF1R and AR are associated with the risk of ovarian cancer development, we next tested whether these miRNAs could exert any noticeable effects on the behavior of ovarian cancer cells." (PMID 39622842, 2024). "Given this, our current finding that flutamide can restore the reduced expression of miR-449a and miR-449b-5p in HR tissues, thereby suppressing CSF1R, provides a mechanistic insight into how flutamide may potentially mitigate the risk of ovarian cancer initiation." (PMID 39622842, 2024). "Given the intratumoral heterogeneity of TAM polarization in ovarian cancer, a strategic combination of macrophage-targeted therapies, such as CSF1R and TREM2 inhibitors, with immunotherapies holds promise for improving clinical outcomes." (PMID 40330466, 2025). "Clinical studies have also highlighted the therapeutic potential of CSF1R inhibitors in various cancers, including ovarian cancer." (PMID 40330466, 2025). "Flutamide also increased miR-449a and miR-449b-5p levels in cancer cell lines leading to reduction of the AR protein levels and colony stimulating factor 1 receptor, both of which contribute to ovarian cancer progression." (PMID 40392873, 2025). "To investigate the importance of CSF-1R in human ovarian cancer patients, we collected tumor tissues from 111 primary ovarian cancer patients and analyzed the relationship between CSF-1R expression and ovarian cancer patient prognosis." (PMID 38303927, 2024). "Using paclitaxel as a model drug in combination with a CSF-1R inhibitor, we explored the antitumor effects of this regimen and the drug safety in the treatment of the ovarian cancer ID8 animal model." (PMID 38303927, 2024). "In conclusion, this study showed a close correlation between CSF-1R and the prognosis of ovarian cancer patients." (PMID 38303927, 2024). "Together, our findings underscore the potential involvement of cellular pathways such as CSF1/CSF1R and AR in the development of epithelial ovarian cancer and the response to flutamide treatment." (PMID 39622842, 2024). "Additional treatments act by suppressing macrophage recruitment through targeting kinase receptors such as colony-stimulating factor 1 receptor (CSF-1R), which is expressed on ovarian cancer cells." (PMID 39802952, 2024). "There are few reports on the effects of targeted inhibition of CSF-1R in combination with chemotherapy on ovarian cancer and the tumor microenvironment." (PMID 38303927, 2024).
ovarian carcinoma (continued). "The relationship between CSF-1R expression and the prognosis of ovarian cancer patients was investigated by analyzing the expression of CSF-1R in ovarian cancer cells via a tissue microarray of primary ovarian cancer." (PMID 38303927, 2024). "The results showed that PLX3397, the inhibitor of CSF-1R, inhibited the proliferation of ovarian cancer cells in a time-dependent and dose-dependent manner." (PMID 38303927, 2024). "We found that CSF-1R is highly expressed in ovarian cancer cells and correlates with poor prognosis." (PMID 38303927, 2024). "The TISIDB database assessed that CX3CR1 gene expression was significantly associated with immunoinhibitors in epithelial ovarian cancer, including HAVCR2 (R = 0.51, P < 2.2e−16) and CSF1R (R = 0.66, P < 2.2e−16)." (PMID 38241595, 2024). "In ovarian cancer preclinical models, CSF-1/CSF-1-R blockade has only been investigated via small-molecule inhibitors as opposed to mAbs." (PMID 35020853, 2022). "Overexpression of CSF1R or its ligand CSF1 is found in various solid tumors, including those associated with breast, prostate, and ovarian cancer, and plays an important role in tumor malignancy and metastasis." (PMID 33796453, 2021). "For CSF1R, several studies have exhibited that its blockade significantly decreases ascites and M2 macrophage infiltration in epithelial ovarian cancer mouse models." (PMID 34094977, 2021). "In an ovarian cancer mouse model, the depletion of macrophages with CSF1R inhibitors restored sensitivity to bevacizumab and paclitaxel in the setting of adaptive resistance." (PMID 33580206, 2021). "For example, a phase I study in patients with solid tumors such as breast and ovarian cancers, evaluated Emactuzumab, an anti-CSF1R treatment, in combination with paclitaxel chemotherapy." (PMID 33276524, 2020). "Thus, leveraging CSF1R blockade in conjunction with ICIs or cytokine-based therapies represents a compelling avenue for enhancing immunotherapy efficacy in ovarian cancer." (PMID 40330466, 2025). "Additionally, GW2580, a selective CSF1R inhibitor, has been shown to normalize tumor vasculature and reduce malignant ascites in experimental ovarian cancer models by limiting M2 macrophage-mediated vascular permeability." (PMID 40330466, 2025). "Similarly, CSF-1R overexpression induced chemoresistance in ovarian cancer cells via AKT and ERK1/2 pathway activation, while knockdown studies indicated that CSF-1R inhibition increased the apoptotic rate of cisplatin-treated tumor cells." (PMID 38254773, 2024). "CSF-1R is expected to be a potential target in ovarian cancer treatment." (PMID 38303927, 2024). "Persistent expression of CSF-1R apparently enhanced the invasiveness of ovarian cancer cells." (PMID 38303927, 2024). "Consistent with CSF1R and AR pathways being known contributors to ovarian cancer progression and initiation and being significantly elevated in HR women, we observed that miR-449a and miR-449b-5p reduced the migration of ovarian cancer cells." (PMID 39622842, 2024). "Moreover, emactuzumab, as monotherapy or plus paclitaxel, as well as LY3022855, plus tremelimumab or durvalumab, are among the CSF-1R antibodies investigated in patients with advanced solid tumors, each showing moderate activity in ovarian cancer patients." (PMID 39003350, 2024). "Introducing mimics of these miRNAs reduced the mRNA and protein levels of AR and colony-stimulating factor 1 receptor (CSF1R, also known as c-fms), both of which are known contributors to ovarian cancer progression, with emerging evidence also supporting their roles in ovarian cancer initiation." (PMID 39622842, 2024). "Therefore, to understand the effect of inhibiting CSF-1R on ovarian cancer cells in vitro, we selected the human ovarian cancer cell line A2780 and the mouse ovarian cancer cell line ID8 for in vitro correlation experiments." (PMID 38303927, 2024).
ovarian carcinoma (continued). "Targeting CSF-1R repolarizes M2-like TAMs to the M1 phenotype, reduces the infiltration of macrophages into tumor tissue, and improves patients’ response to standard treatment in mouse ovarian tumor models and ovarian cancer patients." (PMID 39003350, 2024). "The usefulness of targeting the binding of CSF-1 and CSF1R was shown in a preclinical study, where a mouse model of ovarian cancer that had been intravenously administered a CSF-1R inhibitor (BLZ945) exhibited a decrease and an increase in TAM cells and CD8+ T, respectively." (PMID 36466873, 2022). "CSF1R is the primary receptor responsible for the survival, proliferation, and differentiation of macrophages, making it an ideal candidate to target TAMs in ovarian cancer." (PMID 29228548, 2017). "In the present study, we used two CSF1R inhibitors with different mechanisms of action to determine the effects of CSF1R inhibition in combination with anti-VEGF therapy in the setting of adaptive resistance in ovarian cancer models." (PMID 29228548, 2017). "Therefore, we believe that CSF-1R can be used as a therapeutic target for ovarian cancer." (PMID 38303927, 2024). "Therefore, to understand whether inhibition of CSF-1R can play an anti-ovarian cancer role, we first selected the CSF- 1R small molecule inhibitor PLX3397 for in vitro experimental validation." (PMID 38303927, 2024). "Targeting macrophages is a promising therapeutic approach to ovarian cancer and early encouraging work indicates that CSF-1R blockade, anti-B7-H4 scFvs and anti-CCL22 mAbs may generate potent antitumor responses, which is associated with elimination of regulatory T cells." (PMID 26077607, 2015). "The impact of the combination of CSF-1R inhibitors and chemotherapeutic agents on the TME was characterized, providing more potential targets for the clinical treatment of ovarian cancer." (PMID 38303927, 2024). "mAbs targeted against CCL2 and CSF-1R to reduce TAM recruitment and/or survival have been investigated in phase I clinical trials involving ovarian cancer patients (NCT02526017)." (PMID 35020853, 2022). "Pre-clinical studies investigating GW2580, a CSF-1R inhibitor, demonstrated decreased tumor volume, ascites, and TAM infiltration in ovarian cancer mouse models." (PMID 35565348, 2022). "We showed that CSF1R inhibitors not only deplete macrophages, but also significantly decrease tumor burden when combined with anti-VEGF therapy in multiple models of ovarian cancer." (PMID 29228548, 2017). "Our present study bridges this knowledge gap by showing how these miRNAs modulate the expression of CSF1R and AR in ovarian cells, implicating their significant roles in regulating CSF1/CSF1R and AR signaling pathways during the development of epithelial ovarian cancer in HR women." (PMID 39622842, 2024). "Investigations of CSF-1R antibodies in patients with advanced solid tumors include: 1) AMG 820, emactuzumab, in monotherapy or plus paclitaxel, and LY3022855, plus durvalumab or tremelimumab, each displaying modest activity in ovarian cancer patient subsets." (PMID 35565348, 2022). "In this context, elevated levels of CSF1 and expression of CSF1R have been associated with poor prognosis in different cancers such as breast and ovarian cancer and, consequently, different strategies have emerged to neutralize or inhibit the CSF1/CSF1R signaling in several cancers." (PMID 34298983, 2021). "Notably, our study found that crucial immune repressive receptors—which have gained significant attention in ovarian cancer research, such as TIM3, CSF1R, CTLA4, PD1, and LAG3 as well as inhibitory enzymes such as IDO1—were closely related to ALOX5AP expression." (PMID 34094977, 2021).